FZD2 (frizzled class receptor 2)
Diseases named in the same sentence as FZD2 in open-access papers (continued):
Sharing a sentence is not in itself a finding about the gene and the disease.
Robinow syndrome (5 papers, 2018 to 2025). Robinow syndrome (RS) is a rare genetic syndrome characterized by limb shortening and abnormalities of the head, face and external genitalia. "The mother of the proband carried a truncating FZD2 variant (c.1130G>A; p.Trp377*) and had a milder form of Robinow syndrome (short stature, broad forehead)." (PMID 38967226, 2024). "Genotype–phenotype correlation analysis revealed that individuals with FZD2-associated Robinow syndrome have milder craniofacial phenotypes than those with other gene variants." (PMID 38967226, 2024). "Of these, Frizzled2 (FZD2), coding for a receptor that transduces Wnt signals into cells to regulate their growth, is the second most common Robinow syndrome-causing gene." (PMID 38967226, 2024). "FZD2 is the second most common Robinow syndrome-causing gene, and 17 patients with autosomal dominant Robinow syndrome with missense or truncating variants in FZD2 have been reported." (PMID 38967226, 2024). "Here, they found that expression of either FZD2 variant resulted in the development of craniofacial abnormalities akin to those seen in Robinow syndrome, such as reduced bone formation and increased width of the nose and nasal cavities." (PMID 38967226, 2024). "However, a detailed understanding of the impact of FZD2 variants on the development of Robinow syndrome is missing." (PMID 38967226, 2024). "Therefore, FZD2 missense variants are pathogenic and could lead to the altered craniofacial morphogenesis seen in Robinow syndrome." (PMID 38967226, 2024). "Mutations in genes from WNT pathways, including ROR2, FZD2, WNT5A, DVL1, and DVL3, have all been found to cause Robinow syndrome in humans." (PMID 30521570, 2018). "Alternatively, targeted approaches may focus on downstream pathways such as in utero administration of DKK inhibitors in preclinical studies using humanized mouse models of FZD2 of Robinow syndrome, which showed ability to normalize skeletal growth." (PMID 40100426, 2025). "Of these, receptor tyrosine kinase-like orphan receptor 2 (ROR2) and nucleoredoxin (NXN) are linked to autosomal recessive Robinow syndrome, whereas dishevelled genes (DVL1, DVL2 and DVL3), WNT5A and Frizzled2 (FZD2) have autosomal dominant inheritance (autosomal dominant Robinow syndrome)." (PMID 38967226, 2024). "Human Robinow syndrome (RS) and dominant omodysplasia type 2 (OMOD2), characterized by skeletal limb and craniofacial defects, are associated with heterozygous mutations in the Wnt receptor FZD2." (PMID 36867021, 2023). "In addition to the bulldog DVL2 frameshift mutation, human mutations causing Robinow syndrome have been identified in WNT5A, ROR2, FZD2, DVL1, and DVL3, which are all major components of the WNT5A-ROR pathway." (PMID 30521570, 2018). "Most of the genes implicated in the pathogenesis of Robinow syndrome function in the non-canonical c-Jun N-terminal kinase (JNK)/planar cell polarity (PCP) pathway except for FZD2, DVL1, DVL2 and DVL3, which also operate in the canonical/β-catenin-mediated WNT pathway." (PMID 38967226, 2024). "As multiple genes are involved, the pathogenesis of Robinow syndrome could result from an imbalance of either branch of WNT signaling pathways, as we recently reported for DVL1 variants and others for reported variants in FZD2." (PMID 38967226, 2024). "Most genes that cause Robinow syndrome lie in the non-canonical WNT pathway except for DVLs and FZD2, which also function in the canonical WNT pathway." (PMID 38967226, 2024).
melanoma (4 papers, 2013 to 2022). A malignant, usually aggressive tumor composed of atypical, neoplastic melanocytes. "The highest correlations observed with HMOX-1 in patients with melanoma were with FZD2 (rho = 0.54), KEAP1 (rho = 0.59), MAPK13 (rho = 0.68), the “ferroptosis” gene FTL (rho = 0.58), and CHUK (rho = −0.50)." (PMID 35053476, 2022). "In particular, Wnt5a/FZD2 signaling has been shown to control melanoma Ca2+ homeostasis, cellular migration, and invasion in colon cancer." (PMID 26132195, 2015).
neuroblastoma (4 papers, 2018 to 2024). Neuroblastoma (NB) is the most common solid, extracranial childhood tumor. "One study has shown that FZD-2 stimulated cell proliferation and promoted cell migration in high-risk neuroblastoma by interfering with _β-catenin-dependent and β-catenin-independent signaling pathways." (PMID 33723319, 2021). "FZD2 suppression inhibits the β-catenin-dependent signaling pathway, and its knockdown suppresses tumor growth in neuroblastoma animal models." (PMID 38167429, 2024). "Examples include high FZD1 expression associated with chemoresistance, FZD6 marking highly tumorigenic stem-like cells in mouse and human neuroblastoma, and FZD2-dependent proliferation of neuroblastoma lines." (PMID 29505958, 2018).
colorectal cancer (3 papers, 2019 to 2025). A primary or metastatic malignant neoplasm that affects the colon or rectum. "Additionally, Gujral and colleagues 33 showed that FZD2 drives the EMT and cell migration in colorectal cancer by activating the Fyn and STAT3 signaling pathways." (PMID 31595151, 2019).
endometrial cancer (3 papers, 2019 to 2023). Primary or metastatic malignant neoplasm involving the endometrium (mucous membrane that lines the endometrial cavity). "In endometrial cancer, elevated FZD2 promoted the migration and induced the progression of epithelial-mesenchymal transition (EMT)." (PMID 33618667, 2021). "In addition, EMT promoted by FZD2 also plays an important role in the metastasis of endometrial cancer, therefore suggesting that the invasive behavior of epithelial cells in FA has a cancerogenic aspect." (PMID 37005590, 2023). "In endometrial cancer, FZD2 could modulate the EMT process by activating Wnt signaling pathway." (PMID 33618667, 2021).
liver cancer (3 papers, 2016 to 2025). An epithelial or non-epithelial malignant neoplasm that arises from the liver. "Additionally, FZD2 expression is linked to the mesenchymal phenotype in liver cancer cells, driving increased migration and invasiveness." (PMID 40444048, 2025).
metastatic cancer (3 papers, 2018 to 2023). A carcinoma which has spread from the original site of growth to another anatomic site. "According to the results of in vitro and in vivo experiments, Fzd2 is an oncogene, and overexpression of Fzd2 and signaling through the non-canonical Wnt pathway can promote the development of advanced metastatic cancer." (PMID 33485313, 2021).
oral squamous cell carcinoma (3 papers, 2019 to 2025). "FZD2 showed promise as a diagnostic biomarker in BLCA, BRCA, CHOL, ESCA, HNSC, oral squamous cell carcinoma (OSCC), READ, and STAD, with AUCs of 0.829, 0.808, 0.971, 0.921, 0.955, 0.950, 0.717, and 0.858, respectively." (PMID 40444048, 2025). "An earlier study revealed that FZD2 promotes cell motility and invasiveness in oral squamous cell carcinoma cells via the regulation of the STAT3 pathway." (PMID 31595151, 2019). "Similarly, FZD2 has been shown to promote migration and invasion in oral squamous cell carcinoma (OSCC) through the STAT3 pathway." (PMID 40444048, 2025). "In oral neoplasms, FZD2 promotes the oncogenesis of oral squamous cell carcinoma." (PMID 34986855, 2022). "Although some studies have speculated that FZD2 may contribute to carcinogenesis in oral squamous cell carcinoma cell lines 15-16, the roles of FZD2 in tongue squamous cell carcinoma remain ambiguous." (PMID 31595151, 2019).
adenoma (2 papers, 2013 to 2024). A neoplasm arising from the epithelium. "Adenomas had significantly increased expression of transcription factors E2f5 and Tcf712, Wnt family receptor Fzd2, transcriptional regulator Nfatc3, regulator of the gamma secretase complex Psenen, and Rb." (PMID 38334641, 2024).
Alzheimer disease (2 papers, 2023). A progressive, neurodegenerative disease characterized by loss of function and death of nerve cells in several areas of the brain leading to loss of cognitive function such as memory and language. "Seven of these genes are Alzheimer’s disease-related, six are down-regulated with both Apoer2-ICDs (COX7A2L, FZD2, KIF5A, MAP2K2, PSENEN, RAF1) and one with only the Apoer2-ICD[Δ19] (SLC39A9)." (PMID 37461529, 2023).
bladder cancer (2 papers, 2025). "To assess the possible role of FZD2 in bladder cancer cell functions, we knocked down FZD2 in T24 cells." (PMID 40308577, 2025). "In this study, we identified the critical role of the XIST/miR-15a-5p/MN1/FZD2 signaling axis in explaining gender disparities in bladder cancer prognosis." (PMID 40308577, 2025). "Our data indicate that FZD2 promotes bladder cancer cell proliferation and migration, and that the regulation of these functions by XIST is closely linked to FZD2." (PMID 40308577, 2025). "We discovered that the XIST/miR-15a-5p/MN1/FZD2 signaling axis plays a significant role in regulating the progression of bladder cancer." (PMID 40308577, 2025). "The XIST/miR-15a-5p/MN1/FZD2 signaling axis was found to play a critical role in promoting bladder cancer progression." (PMID 40308577, 2025). "Functional experiments demonstrated that XIST knockdown significantly inhibited bladder cancer cell proliferation, migration, and invasion, effects which could be reversed by FZD2 overexpression." (PMID 40308577, 2025). "We further investigated whether the effects of XIST on bladder cancer cell functions are mediated through FZD2." (PMID 40308577, 2025). "Our analysis revealed significant upregulation of FZD2 in multiple malignancies, including stomach adenocarcinoma (STAD), bladder cancer (BLCA), and cholangiocarcinoma (CHOL)." (PMID 40444048, 2025). "However, prior reports on FZD2 expression specifically in bladder cancer are lacking." (PMID 40308577, 2025).
head and neck squamous cell carcinoma (2 papers, 2019 to 2025). A squamous cell carcinoma that arises from any of the following anatomic sites: lip and oral cavity, nasal cavity, paranasal sinuses, pharynx, larynx, and salivary glands. "In our results, according to the TCGA and Oncomine databases, FZD2 is highly expressed in head and neck squamous cell carcinoma and is closely related to the survival of patients." (PMID 31595151, 2019).
lung adenocarcinoma (2 papers, 2022 to 2025). A carcinoma that arises from the lung and is characterized by the presence of malignant glandular epithelial cells. "Based on the TCGA data, we constructed a lung adenocarcinoma prognosis model, and we found five key Wnt signaling pathway related genes, including AXIN1, CTNNB1, LEF1, FZD2, FZD4." (PMID 36703749, 2022).
metastatic prostate carcinoma (2 papers, 2019 to 2022). A carcinoma that arises from the prostate gland and has spread to other anatomic sites. "In addition, FZD2, FZD4, and FZD8 mRNA upregulation is also reported in human metastatic prostate cancer cell lines, and FZD2, FZD7, and FZD8 mRNA levels are increased in hormone depleted LNCaP cells." (PMID 35204808, 2022). "It has been reported that the activation of the WNT5A/FZD2-induced noncanonical WNT pathway (NCWP) promotes the progression of advanced and metastatic prostate cancer and induces the epithelial-to-mesenchymal transition (EMT) in certain cancers." (PMID 31595151, 2019).
adenomyosis (1 paper, 2023). The growth of endometrial tissue inside the muscular wall of the uterine corpus. "If we look at the changes of single genes, it is striking that Frizzled class receptor 2 (FDZ2) is the only gene that is significantly upregulated in adenomyosis compared to DIE." (PMID 37005590, 2023).
adrenocortical carcinoma (1 paper, 2025). "CNA of FZD2 was pronounced in uveal melanoma (UVM) and adrenocortical carcinoma (ACC), where copy number deletion accounted for all genetic alterations of FZD2 in those cancers." (PMID 40444048, 2025).
autosomal dominant omodysplasia (1 paper, 2018). Autosomal dominant form of omodysplasia. "Presented are two patients with autosomal dominant omodysplasia and mutations in the FZD2 gene." (PMID 30455931, 2018). "This alteration was likely not reported in the prior investigational WES due to the association of the FZD2 gene and autosomal dominant omodysplasia not yet being reported." (PMID 30455931, 2018).
autosomal dominant Robinow syndrome (1 paper, 2024). Autosomal dominant Robinow syndrome (DRS) is the more common type of Robinow syndrome (RS) characterized by mild to moderate limb shortening and abnormalities of the head, face and external genitalia. "Given the significant overlap in phenotypes between OMODII and autosomal dominant Robinow syndrome, OMODII is currently recognized as part of autosomal dominant Robinow syndrome caused by FZD2 variants." (PMID 38967226, 2024). "Here, we focused on two autosomal dominant Robinow syndrome FZD2 variants and how they affect craniofacial development and WNT signaling." (PMID 38967226, 2024).
basal cell carcinoma (1 paper, 2020). A carcinoma involving the basal cells. "Indeed, the genes driving the basal cell carcinoma pathway are FZD9, FZD7, FZD2, DVL1, and AXIN1, all playing a role in the Wnt signaling pathway, which has already been linked to AD and PD." (PMID 33362460, 2020).
brain injury (1 paper, 2020). Acute and chronic (see also brain INJURIES, CHRONIC) injuries to the brain, including the cerebral hemispheres, CEREBELLUM, and brain STEM. "In hypothalamus, Fzd2 which decreased in winter, attenuates pathological Ca++ increase in a rat model of traumatic brain injury." (PMID 33536943, 2020).
cardiac hypertrophy (1 paper, 2021). "Our group was the first to describe the upregulation of the expression of the seven transmembrane (7TM) receptor Frizzled-2 (FZD2) in cardiac hypertrophy and MI." (PMID 33494313, 2021).
cerebral infarction (1 paper, 2025). An ischemic condition of the brain, producing a persistent focal neurological deficit in the area of distribution of the cerebral arteries. "We further analyzed the expression differences of Pip5k1c, Nlgn2, Fzd2, Cd86, Agpat1, and Degs2 between the cerebral infarction at 3, 6, and 12 h and the control group." (PMID 40520774, 2025). "The AUC values of Pip5k1c, Nlgn2, Fzd2, Cd86, Agpat1, and Degs2 were all 1, suggesting that Pip5k1c, Nlgn2, Fzd2, Cd86, Agpat1, and Degs2 have good sensitivity and specificity for the diagnosis of cerebral infarction." (PMID 40520774, 2025).
cervical carcinoma (1 paper, 2021). A carcinoma arising from either the exocervical squamous epithelium or the endocervical glandular epithelium. "miRNAs miR-17-5p, miR-30a-5p, miR-30a-3p, and miR-34a also decrease Fzd2 expression and inhibit tumorigenesis in cervical carcinoma, esophageal squamous cell carcinoma, and breast cancer, respectively." (PMID 34671643, 2021). "miR-17-5p also increases drug sensitivity to cervical carcinoma cells treated with Cas-II-gly by inhibiting both Fzd2 and the lncRNA MALAT1." (PMID 34671643, 2021).
cocaine addiction (1 paper, 2025). "KEGG pathway enrichment analysis indicated that FZD2 is involved in aminoacyl-tRNA biosynthesis, glycosaminoglycan biosynthesis (chondroitin sulfate/dermatan sulfate), and cocaine addiction pathways." (PMID 40444048, 2025).
colorectal adenocarcinoma (1 paper, 2025). The most common type of colorectal carcinoma. "Our findings demonstrate a positive correlation between FZD2 expression and TMB in cancers such as colorectal adenocarcinoma (COAD), supporting the hypothesis that FZD2 targeting could improve ICI efficacy, especially in tumors with high TMB." (PMID 40444048, 2025).
colorectal adenoma (1 paper, 2021). An adenoma that arises from the colon or rectum. "FZD2 is highly expressed in premalignant lesions preceding esophageal adenocarcinoma but is decreased in colorectal adenomas compared to normal tissue, suggesting FZD2 could be targeted differently to intercept early lesions depending on the tissue type." (PMID 34604862, 2021).
idiopathic pulmonary fibrosis (1 paper, 2011). Idiopathic pulmonary fibrosis (IPF) is a nonneoplastic pulmonary disease that is characterized by the formation of scar tissue within the lungs in the absence of any known cause. "Konigshoff and colleagues confirmed the up-regulation of WNT1, WNT7B and WNT10B, FZD2, FZD3, β-catenin, and LEF1 expression in the lungs of individuals with idiopathic pulmonary fibrosis compared to transplant donor lung." (PMID 21490961, 2011).
injury (1 paper, 2016). Damage inflicted on the body as the direct or indirect result of an external force, with or without disruption of structural continuity. "WNT-5A has been shown to bind to FZD2 inducing intracellular calcium release and PKC activation in Xenopus and zebrafish embryos and WNT-5A-FZD2-induced calcium spikes in neurons are implicated in traumatic brain injury." (PMID 26514730, 2016).
ischemic stroke (1 paper, 2025). A stroke disorder caused by obstruction of blood flow to the brain, due to thrombotic (local blood clot formation) or embolic (due to a blood clot or other material traveling from another site) event. "Single-gene GSEA revealed that the identified signature genes (Pip5k1c, Nlgn2, Fzd2, Cd86, Agpat1, and Degs2) converge on neuroinflammatory and apoptotic pathways critical in ischemic stroke pathogenesis." (PMID 40520774, 2025). "The results demonstrated that, in comparison to the control group, the expression of Pip5k1c, Nlgn2, Fzd2, Cd86, Agpat1, and Degs2 showed a downward trend with an increase in the onset time of ischemic stroke, and the decrease was most significant in the MCAO_12 h group (p < 0.01)." (PMID 40520774, 2025).
latent infection (1 paper, 2019). "In normal to latent infections, we identified eight genes, of which three genes (FZD2, NDUFS8, NLRC4) were up-regulated, and another five genes (CCL4, IL1B, IL1A, TNF, AREG) were down-regulated." (PMID 31749827, 2019).
lung diseases (1 paper, 2018). "Further analysis of expression of FzD2 and wnt ligands in Treg cells from patients with lung diseases could provide a better understanding of a disease specific role for Treg cell function in health and disease." (PMID 30546835, 2018).
medulloblastoma (1 paper, 2013). A malignant, invasive embryonal neoplasm arising from the cerebellum. "Likewise, F2R and FZD2, both of which were found to be significantly over-expressed in all subgroups of medulloblastoma tumors in our dataset, were also both highly expressed in all tumor groups in previously published larger tumor cohorts." (PMID 24252460, 2013).
metastatic tumors (1 paper, 2015). "WNT5A and WNT5B are ligands for and bound by FZD2 and FZD4, and this binding has been shown to drive EMT and is elevated in metastatic tumors." (PMID 26572553, 2015).
myocardial infarction (1 paper, 2025). Gross necrosis of the myocardium, as a result of interruption of the blood supply to the area, as in coronary thrombosis. "Additionally, studies indicate that FZD2 prevents adult mouse cardiomyocytes from re-entering the cell cycle by inhibiting Yes-associated protein (YAP), thus protecting the myocardium after myocardial infarction by preventing excessive cardiomyocyte proliferation and fibrosis." (PMID 41000338, 2025).
non-small cell lung carcinoma (1 paper, 2020). A group of at least three distinct histological types of lung cancer, including non-small cell squamous cell carcinoma, adenocarcinoma, and large cell carcinoma. "OMP-18R5 (Vantictumab) targets the FZD1, FZD2, FZD5, FZD7, and FZD8 frizzled protein receptors to block WNT signaling are being investigated in phase I clinical trials in breast, pancreatic, and non-small cell lung cancer." (PMID 32758244, 2020).
Noonan syndrome (1 paper, 2019). Noonan Syndrome (NS) is characterized by short stature, typical facial dysmorphism and congenital heart defects. "Variants in FZD2 and LZTR1 were described in individuals with Robinow syndrome-like phenotype (FZD2) and Noonan syndrome (LZTR1), respectively." (PMID 30809043, 2019).